MS4A4A (membrane spanning 4-domains A4A)
Diseases named in the same sentence as MS4A4A in open-access papers (continued):
Sharing a sentence is not in itself a finding about the gene and the disease.
tumor (40 papers, 2019 to 2025). "MS4A4A, the other member of tetraspanins characteristically expressed in tumor-associated macrophages, also co-ligates with dectin-1 and mediates tumor cytotoxicity by enhancing IFN-γ production and NK cell activation." (PMID 33946381, 2021). "For example, 6phosphofructo-2-kinase/fructose-2,6-bisphosphatase 3 (PFKBP3) involved in glycolysis is a target of six significantly altered miRNAs in EVs whereas Membrane Spanning 4-Domains A4A (MS4A4A) which belongs to tumor-associated macrophages is a target of four EV-linked miRNAs." (PMID 38891019, 2024). "To inspect the clinical implications of cell communications between CAFs, macrophages, endothelial cells, and tumour cells, we detected expression associations between signature genes (FGF7/THBS1/MS4A4A/ZEB1) and tumour miRNAs." (PMID 38778448, 2024). "The results above suggest that MS4A4A‐positive macrophage clusters are more abundant in tumor tissue, spatially and in terms of expression levels." (PMID 38997808, 2024). "The relationship between IDO1 and marker genes of tumor-associated macrophages (TAMs; CCL5, CD68, and IL10), M1 (IRF5, NOS2, and PTGS2), and M2 (CD163, VSIG4, and MS4A4A) macrophages was analyzed." (PMID 39351094, 2024). "MRC1 is a well‐known marker gene for M2 macrophages, while MS4A4A is thought to have a role in macrophage function and polarization, particularly in the expression of M2 macrophages that are known to promote tumor development in GBM." (PMID 38997808, 2024). "The results suggest that the knockout of MS4A4A enhances the activity of tumor‐infiltrating CD8+ T cells, as determined by evaluating their activity through the expression levels of IFN‐γ and Ki67." (PMID 38997808, 2024). "On the same line, Membrane Spanning 4-Domains A4A (MS4A4A)+ macrophages have been described for their anti-tumor function, in view of their ability to release pro-inflammatory cytokines, including IL-15 and IL-18, upon engagement of Dectin-1 by tumor cells." (PMID 37298470, 2023). "We found that VCAN and MS4A4A expression was higher in tumor tissue compared with adjacent tissue of Neutrophils." (PMID 36569220, 2022). "Pearson correlation analysis further showed that OPN was positively associated with M2 macrophage markers (CD163, VSIG4, MS4A4A, CX3CR1, and MRC1) and tumor-associated macrophage (TAM) markers (CCL2, CD68, and IL10)." (PMID 35669197, 2022). "In macrophages, MS4A4A was more highly expressed in adjacent tissue samples than tumor samples (P value = 0.007)." (PMID 36569220, 2022). "Our data report a strong correlation between GPX7 expression with the M2 macrophages markers (CD163, VSIG4, MS4A4A), implying a potential role for GPX7 in the polarization of tumor-associated macrophages (TAM) in LGG169." (PMID 35440701, 2022). "MS4A4A was reported to be a fundamental molecule in tumor-infiltrating macrophages as well as in dectin-1-dependent activation of NK cells in cancer." (PMID 33986748, 2021). "Based on the experimental findings, we could conclude that in a physiological environment, the surface molecule MS4A4A on macrophages influences tumor growth and progression by regulating macrophage polarization and function." (PMID 38997808, 2024). "Interestingly, although major macrophage-specific mRNAs (CD68, CD14, and ITGAM) were relatively unchanged, the mRNAs associated with an M2 phenotype (CSFR1, CD163, MS4A4A, and CRC1) were decreased, suggesting a change toward a more M1, anti-tumor status." (PMID 38744944, 2024). "Based on the findings before, we hypothesize that the elevated MS4A4A activity contributes to tumor evasion by involving itself in the differentiation of M1 and M2 macrophages." (PMID 38997808, 2024). "Further temporal analysis indicates that MS4A4A may play a role in differentiating and functionally regulating M1 and M2 macrophages, consequently impacting tumor growth and development." (PMID 38997808, 2024).
tumor (continued). "Research has shown that in animal models inhibition of MS4A4A or the use of anti‐MS4A4A monoclonal antibodies as therapy could modify the immune microenvironment of the tumor." (PMID 38997808, 2024). "In highly invasive tumor samples, a significant upregulation of MS4A4A can be observed." (PMID 38997808, 2024). "It has been demonstrated that MS4A4A was expressed in macrophages and enacted anti-tumor functions." (PMID 37622120, 2023). "The expression of MS4A4A in tumor tissue was lower than normal tissue." (PMID 36569220, 2022). "In monocytes, VCAN expression was higher in adjacent tissue samples than tumor samples (P value-adj = 9.99E − 84); ANGPT2 was not highly expressed in immune cells of tumor samples or adjacent tissue samples; MS4A4A was highly expressed in monocytes of tumor samples (P value-adj = 1.02E − 14)." (PMID 36569220, 2022). "Pearson correlation coefficients were calculated, and the results indicated that BGN presented the strongest correlations with TIIC markers for monocytes (CD86, CD115), tumor-associated macrophages (TAMs) (IL-10, CCL2, CD68), M2 macrophages (CD163, VSIG4, and MS4A4A) and Tregs (FOXP3, CCR8, TGFβ)." (PMID 35096572, 2021). "GNB4 expression was notably related to the tumor-associated macrophage (TAM) markers CCL2 (Cor = 0.527, P = 1.64e−28), IL10 (Cor = 0.61, P = 5.02e−40), M2 macrophage marker CD163 (Cor = 0.66, P = 1.01e−48), VSIG4 (Cor = 0.64, P = 5.17e−45), and MS4A4A (Cor = 0.723, P = 1.26e−62)." (PMID 35756485, 2022). "After adjusting for tumor purity, CXCL8 expression showed strong positive correlations with M2 macrophage markers (CD163, VSIG4, MS4A4A) in Gr." (PMID 41432874, 2025). "In vivo models, including subcutaneous and orthotopic transplantation in mice, were utilized to evaluate the effects of MS4A4A knockout and combined immune checkpoint blockade (ICB) therapy on tumor growth and response to PD‐1 immunotherapy." (PMID 38997808, 2024). "We found that FGF7+/THBS1+ myofibroblasts, MS4A4A+ macrophages, and ZEB1+ endothelial cells were tumour‐enriched cell subtypes in MCA, contributing to MCA progression through crosstalk with MUC1+ cancer cells." (PMID 38778448, 2024). "To replicate the interaction between tumor cells and macrophages within the TME, we generated CM from mouse GBM cells and utilized it to culture BMDMs with varying levels of MS4A4A expression, prompting their transformation into TAMs." (PMID 38997808, 2024). "The results were in accordance with the difference analysis of hub genes (ANGPT2, VCAN, MS4A4A, and FOS) between tumor tissues and normal tissue." (PMID 36569220, 2022). "Western blot was conducted to evaluate the expression of angiopoietin-2 (ANGPT2), FosB, MS4A4A, and Versican (VCAN) in tumor tissue and normal tissue." (PMID 36569220, 2022). "According to the tumor grades, in TCGA database, compared with WHO II and III, the transcription levels of MS4A4A, MS4A4E, MS4A6A, MS4A7, TMEM176A, and TMEM176B were the highest in WHO IV." (PMID 35734424, 2022). "Similarly, the possibility of crosstalk between tumour and macrophage spots was assessed by the expression signature of the MUC1 and MS4A4A genes." (PMID 38778448, 2024). "In this study, we found that the hub genes including VCAN MS4A4A, and FOS could regulate the differentiation of monocytes in the tumor environment." (PMID 36569220, 2022). "Based on the founding that tumor suppressor gene ENDOU was negatively correlated with M2 markers of CD163, VSIG4, and MS4A4A, we speculated that ENDOU may also inhibit macrophages M2 polarization in tumor microenvironment." (PMID 33614471, 2020). "However, the role of MS4A4A, a novel cell surface marker for M2-like macrophages and plasma cells, has not yet been uncovered clearly in carcinogenesis and tumor progression." (PMID 31781506, 2019).
tumor (continued). "The markers of M2 macrophages (CD163, VSIG4, and MS4A4A) all showed significant negative correlation coefficient with ENDOU, implicating potential role of ENDOU in tumor infiltrating M2 macrophages." (PMID 33614471, 2020).
cancer (16 papers, 2020 to 2025). A tumor composed of atypical neoplastic, often pleomorphic cells that invade other tissues. "Previous studies have also shown that a high level of MS4A4A expression is significantly associated with a poor prognosis in various cancers." (PMID 39457694, 2024). "It is known that MS4A4A can promote T cell exhaustion, and is associated with poor prognosis in several cancers." (PMID 39315092, 2024). "MS4A4A is a protein associated with immune cell activation, has been shown to be involved in immune escape, and targeting this protein could restore immune function and enhance the efficacy of cancer immunotherapies." (PMID 40655153, 2025). "The results before indicate that MS4A4A is markedly overexpressed in TAMs across different cancers, including GBM." (PMID 38997808, 2024). "To conduct a comprehensive analysis, we performed a series of studies to gain a deeper understanding of the expression patterns of MS4A4A in various types of cancer and its significance in macrophage development and function." (PMID 38997808, 2024). "Subsequently, we analyzed MS4A4A expression in various cancers using the GEPIA database." (PMID 38997808, 2024). "Cancer development is known to be influenced by VSIG4 and MS4A4A, respectively, blocking T-cell activation and activating NK-cell-mediated resistance to metastasis." (PMID 35647201, 2022). "Interestingly, among pan-cancer, LGG showed the most significant correlation between GLA with CD86 (P=4.52e-27), CSF1R (P=8.17e-09),CCL2 (P=3.98e-14), CD68 (P=2.37e-34), IL10 (P=3.29e-21), IRF5 (P=8.5e-25), CD163 (P=3.8e-26), VSIG4 (P=9.17e-16) and MS4A4A (P=1.39e-21)." (PMID 37057282, 2023).
infection (2 papers, 2014 to 2022). The state of being infected such as from the introduction of a foreign agent such as serum, vaccine, antigenic substance or organism. "Ms4a4a had a 2.3-fold increase at 1 wk (p<0.015), and 1.6-fold change at 4 wks post-infection (p<0.011)." (PMID 36490282, 2022).
MS4A4A also shares sentences with these, for which no sentence is quoted: breast carcinoma (2 papers); atherosclerosis (1); cardiovascular diseases (1); infectious disease (1); Kawasaki disease (1); lung carcinoma (1); melanoma (1); metastatic tumors (1); neurodegenerative disease (1); pneumonia (1); respiratory syncytial virus infections (1); tuberous sclerosis (1); urinary tract infection (1); vascular dementia (1).